LINC00920 (long independently transcribed non-coding RNA 920)
Synonyms: CALIC; LINRIS
Gene: Long non-coding RNA gene on chromosome 16 (66,408,504 to 66,412,135, forward strand). Ensembl gene ENSG00000246898.
Diseases named in the same sentence as LINC00920 in open-access papers:
LINC00920 is named in the same sentence as 7 diseases in open-access papers, as found by Europe PMC text mining. Sharing a sentence is not in itself a finding about the gene and the disease. The quoted sentences say what the papers report.
colorectal cancer (10 papers, 2021 to 2023). A primary or metastatic malignant neoplasm that affects the colon or rectum. "For example, LINC00920 blocked the ubiquitination of IGF2BP2 and maintained the MYC‐mediated glycolysis process in colorectal cancer." (PMID 35789547, 2023).
LINC00920 also shares sentences with these, for which no sentence is quoted: tumor (5 papers); cancer (2); colon cancer (2); esophageal squamous cell carcinoma (1); gastric cancer (1); pancreas ductal adenocarcinoma (1).